TNF (tumor necrosis factor)
Diseases named in the same sentence as TNF in open-access papers (continued):
Sharing a sentence is not in itself a finding about the gene and the disease.
asthma (continued). "Significant downregulation of MHCII, CD40 and TNF-α expression in the asthma pathway, blocking acute inflammatory responses such as bronchospasm, edema and airflow obstruction." (PMID 36245510, 2022). "M1 macrophages and M1 cytokines (IL-6, IL-1β, and TNF-α) are involved in neutrophilic airway inflammation in asthma." (PMID 35572500, 2022). "GO and KEGG results showed that the main pathways of YPF in treating asthma include TNF signaling pathway and PI3K-Akt signaling pathway." (PMID 36105239, 2022). "TNF-α is a representative pro-inflammatory cytokine that plays a critical role in the pathogenesis of inflammatory diseases, such as asthma and allergic inflammation." (PMID 35130903, 2022). "Representatively, the eosinophil, a major cell type activated by TNF-α, has a key role to mediate pulmonary inflammation and promote airway remodeling by producing IL-13, resulting in mucus hypersecretion in asthma." (PMID 35335934, 2022). "The lungs of patients with asthma are in a state of inflammation, showing high levels of TNF-α and IL-6 in lung tissue and BALF, mainly released by activated macrophages." (PMID 35682783, 2022). "TNF-α is a representative cytokine whose expression rapidly increases in acute inflammation and affects pulmonary diseases (asthma, acute lung injury, acute respiratory distress syndrome)." (PMID 36613305, 2022). "Beyond Th2 cytokines, SAT also reduced the levels of other potent proinflammatory cytokines (IL-1β, IL-6, and TNF-α) which also plays a key role in asthma pathophysiology and progression, accounting to disease severity." (PMID 36312895, 2022). "To further characterize the impact of IL-6/TNF inhibition in asthma we used a high concentration of HDM, administrated intratracheally, to induce more abundant inflammatory response and tissue remodeling in mice." (PMID 35408882, 2022). "IL-33 and TNF levels were significantly higher in patients with CPA than in those with asthma (p < 0.05)." (PMID 35628692, 2022). "Previous studies found that fisetin can improve the asthma symptoms of asthmatic mice and reduce TNF-α expression in the BALF." (PMID 35565807, 2022). "Taken together, our results provide evidence for therapeutic potential of combined IL-6/TNF inhibition in severe steroid-resistant asthma." (PMID 35408882, 2022). "In several studies, administration of TNF inhibitors also demonstrated encouraging results in mouse models of asthma." (PMID 35408882, 2022). "Systemic nonallergic inflammation, with Type 1 helper T (Th1)-predominant immune patterns such as elevated levels of IL-6, tumor necrosis factor (TNF)-α, and interferon (IFN)-γ, is another potential underlying mechanism of the obese asthma phenotype." (PMID 35889925, 2022). "To evaluate the potency of combined cytokine inhibition, we simultaneously administrated IL-6 and TNF inhibitors to BALB/c mice with HDM-induced asthma." (PMID 35408882, 2022). "On the other hand, in non-T2 asthma models, after epithelial injury, IL-6, TNF, and IL-1a production are stimulated, and neutrophilic inflammation is induced." (PMID 36326393, 2022). "The results showed that the progeny of the obese mice displayed exacerbated responses and intense lung remodeling in the OVA-induced asthma model, which are featured by elevated IL-4, IL-13, TNF-α, TGF-β levels, leukocyte infiltration and collagen deposition." (PMID 36051916, 2022). "The ADAM17 is involved in TNF-α production, and the association between ADAM17 and asthma has recently been demonstrated through animal experiments." (PMID 35130903, 2022). "When activated by FcεRI, mast cells release IL-1β, IL-6, IL-13, and TNF-α, which are involved in the pathology of asthma." (PMID 35266441, 2022). "We first used TNF-α to treat human ASM cells to establish an in-vitro asthma model and then detected miR-15b-5p expression in ASM cells by RT-qPCR, revealing that miR-15b-5p expression was inhibited in TNF-α-stimulated ASM cells compared with the blank group." (PMID 35172671, 2022).
asthma (continued). "TH2 mediators, TNF-α, IL-5, IL-4, IL-1ß play primary role in coordinating various inflammatory mechanisms in asthma." (PMID 38143476, 2022). "Considering the importance of airway epithelial cells in asthma, we then selected TNF-a to stimulate Beas-2B cells and thus observe the effect of the TL1A/DR3 axis and EMT." (PMID 35359966, 2022). "TNF-α has been shown to autoregulate its expression and induce adhesion molecule expression in asthma, and contribute to the development of asthma by enhancing IL-23/Th17 and Th2 immune responses." (PMID 35546400, 2022). "IL-1β release mediates the release of other inflammatory cytokines, including TNF-α and IL-6, which play essential roles in the pathogenesis of pulmonary diseases such as asthma, pulmonary fibrosis, and COPD." (PMID 36432032, 2022). "We determined the effect of miR-155 deficiency on FcεRI-induced production of the proinflammatory cytokines TNF and IL-6, and the mucus-promoting cytokine IL-13, which plays a prominent role in asthma." (PMID 36211602, 2022). "TNF-α promotes the secretion of related inflammatory mediators (such as IL-4) to participate in the occurrence and development of asthma and is one of the important reasons for the persistence of airway inflammation." (PMID 35399628, 2022). "KEGG enrichment results showed that various targets of YPF served crucial roles in asthma-related pathways, such as the TNF signaling pathway, PI3K-Akt signaling pathway, and IL-17 signaling pathway." (PMID 36105239, 2022). "The peripheral blood mononuclear cells (PBMCs), NF-κB activation, and TNF-α of asthma patients and healthy people were analyzed, and puerarin was given to asthma patients." (PMID 36358493, 2022). "TNF-α is a well-known important cytokine in patients with asthma, which plays a central role in the development of AHR and other features of asthma." (PMID 34594225, 2021). "TNF-α has been confirmed that it was involved in the pathophysiology of a number of inflammatory lung diseases, such as asthma, chronic bronchitis and ARDS." (PMID 34305604, 2021). "Further studies are warranted to clarify the role of PRA in the treatment of asthma via the TNF-α signaling pathway." (PMID 34557554, 2021). "The EA group demonstrated a higher serum TNFα level than in EC, and elderly asthma patients had higher level of sTNF RI than younger ones." (PMID 34112152, 2021). "The inflammatory process also involves the synthesis of pro-inflammatory cytokines such as IL-1β, IL-6, TNFα, and TGFβ, which also contribute to asthma pathogenesis." (PMID 33418879, 2021). "Cannabidiol treatment also decreased the levels of IL-4, IL-5, IL-13, IL-6 and tumor necrosis factor α (TNF-α) in an experimental model of asthma in rats, consequently reducing airway inflammation and fibrosis." (PMID 33920748, 2021). "In all patients with asthma, the TNFα, IL-6 and sTNF RI levels were elevated compared to the control group." (PMID 34112152, 2021). "The Childhood Environment and Allergic Diseases Study from Taiwan suggested that higher urine phthalate levels were related to lower tumor necrosis factor-α (TNF-α) methylation levels, potentially exacerbating asthma." (PMID 33836808, 2021). "TNF-α levels in patients with severe asthma are higher than those in patients with mild to moderate asthma and controls." (PMID 33503170, 2021). "Our findings indicate that BMI was positively correlated with sTNF RI, TNF-α and IL-6 but only in younger patients with asthma, which suggests that systemic inflammation in elderly is modified by also other factors." (PMID 34112152, 2021). "In the elderly asthma patients, a positive correlation was found between miRNA-146a and IL-8, while miRNA -126a was negatively correlated with TNF-α." (PMID 34112152, 2021). "Asthma‐2 (n = 19) combined a pro‐inflammatory signature, with a Th2 and innate immune response with upstream modulators of IL‐1β, TNF, IL‐13, IL‐15, and IFNγ." (PMID 34962717, 2021).
asthma (continued). "Asthma is characterized by chronic inflammatory infiltration caused by inflammatory cells and immune cells, and inhibition of TNF-α, IL-1β, IL-17, IL-4, and IL-6 contributes to improving asthma." (PMID 35069542, 2021). "The asthma pathway map of our study indicates that TNF-α is the key target of PRA for the treatment of asthma." (PMID 34557554, 2021). "It was also found that Rg1 effectively suppressed allergic airway inflammation of asthma partly through the TNF-α/NF-κB pathway." (PMID 33575363, 2021). "The amount of TNF-α is also increased in the airways of patients with severe steroid-resistant asthma." (PMID 33418879, 2021). "Patients with asthma had significantly higher levels of IL-1β (19.74±16.77 vs. 2.63±5.22 pg/mL), IL-6 (7.55±8.65 vs. 2.37±2.47 pg/mL), and TNF-α (12.70±12.03 vs. 4.82±3.97 pg/mL) than the controls." (PMID 33503170, 2021). "PRKCA is associated with both BMI and asthma simultaneously, along with other genes with pleiotropic effects like leptin (LEP), and tumor necrosis factor (TNF)." (PMID 33791298, 2021). "Our asthma patients demonstrated significantly elevated proinflammatory cytokine levels (IL-6, TNFα and sTNF RI) compared to healthy controls." (PMID 34112152, 2021). "TNF-a, a proinflammatory cytokine, plays key roles in the modulation of inflammation in different diseases, like asthma, and also in exosome biogenesis." (PMID 33794910, 2021). "On the other hand, Etanercept, a recombinant fusion protein based on TNF receptor 2, significantly improved lung function in patients with severe asthma and high TNF levels in the sputum." (PMID 34084159, 2021). "Murine asthma models have shown that exposure to PM increased neutrophil infiltration by increasing tumor necrosis factor alpha and interferon gamma excretion." (PMID 34445977, 2021). "Th17 cells also produce other pro-inflammatory cytokines such as IL-6 and tumor necrosis factor-α, which play trivial roles in the inflammatory cascade stimulated in the state of asthma." (PMID 33980319, 2021). "The benefit reported from the use of vitamin C in physical training includes attenuation of bronchoconstriction and asthma, neutrophil monocyte accumulation in active muscles, and secretion of IL-1, IL-β, and TNF-α." (PMID 34564191, 2021). "Patients with asthma had significantly higher levels of IL-1β (19.74±16.77 vs. 2.63±5.22 pg/mL), IL-6 (7.55±8.65 vs. 2.37±2.47 pg/mL), and tumor necrosis factor-α (12.70±12.03 vs. 4.82±3.97 pg/mL) compared with the controls." (PMID 33503170, 2021). "In this study, for the first time, we found that CCL21 levels in patients with asthma were lower than those in healthy controls, and the levels of IL-1β, IL-6, and TNF-α were higher in patients with asthma than in healthy controls." (PMID 33503170, 2021). "As shown by the analysis results of the PPI network topology, 13 key targets were screened, and most were inflammatory cytokines, it is worth to note that IL-6, TNF-α, and IL-10 play an important role in the development of asthma." (PMID 34880921, 2021). "Due to its potential impact on the development of asthma, TNF-α is under intense investigation as a therapeutic target." (PMID 34211985, 2021). "In the inflammatory response, proinflammatory cytokines, such as IL-1β, IL-6, and TNF-α, activate the body's immune system and promote the aggregation and activation of inflammatory cells, which plays a crucial role in the process of asthma." (PMID 34966437, 2021). "All patients with asthma demonstrated elevated TNFα, IL-6 and sTNF RI levels compared to controls (p = 0.026, p = 0.03 and p < 0.001 respectively)." (PMID 34112152, 2021). "In the majority of asthma patients, primary bronchial epithelial cells were hyperresponsive to IL-17A and proinflammatory stimuli such as TNF-α, reflected by an enhanced production of inflammatory mediators such as CXCL-8, and corticosteroid insensitivity." (PMID 34221070, 2021).
asthma (continued). "Cytokines (IL‐6, TNF‐α, and IL‐1β) by bronchial epithelial cells promotes the development of asthma." (PMID 34342160, 2021). "The largest number of unique genes were revealed for the double active Lω treatment group (122 genes), which were mainly biologically related to T cell receptor signalling and related signal transduction pathways, TNF and NFκB signalling as well as asthma." (PMID 34193262, 2021). "In this study, we examined the serum levels of CCL21, IL-1β, IL-6, and TNF-α in patients with asthma and healthy controls." (PMID 33503170, 2021). "Our analysis indicated multiple pathways closely related to the effect of ACG on asthma, including the TNF pathway, the TLR pathway, the Th17 cell differentiation-related pathway, the NOD-like receptor pathway and the NF-kappaB pathway." (PMID 33645621, 2021). "Asthma is a chronic inflammatory airway disease in which interleukin-4 (IL-4), IL-13, and TNF-α are involved." (PMID 32139393, 2020). "In contrast, pediatric patients with asthma have demonstrated a possibly altered ineffective Th1 immune response, resulting in lower TNF-α responses from C. pneumoniae infected PBMCs." (PMID 32054098, 2020). "Evidence suggests that β2AR dysfunction can manifest in an inflammatory milieu due to inflammatory cytokines associated with severe asthma and airway remodeling such as TGF-β1, IL-13, and TNF-α." (PMID 33032603, 2020). "As we all know, molecules such as IL-4, IL-6, TNF-α, Ig-E, and Th17cell played key roles in the pathological process of asthma." (PMID 32831980, 2020). "As inflammation is widely associated with asthma symptoms, we measured the inflammatory indicators in BALF, including IL-1β, IL-6, TNF-α, TGF-β, and IFN-γ." (PMID 33456673, 2020). "Undoubtedly, former studies have revealed that TNF-α plays a central role in the pathogenesis of refractory asthma, particularly, in the remodeling process and steroid responsiveness." (PMID 32054098, 2020). "In our study, the ability of a GC (dexamethasone) to inhibit TNFα-induced IL-8 release was reduced in PBMCs obtained from patients with severe asthma compared with those obtained from patients with mild/moderate asthma or healthy subjects." (PMID 32112175, 2020). "TNFα is present in high concentrations in bronchoalveolar fluid derived from the airways of asthma patients." (PMID 32435260, 2020). "TNFα, at increased levels leads to the development of heightened inflammatory responses in asthma and COPD." (PMID 32448302, 2020). "It has been widely accepted that inflammatory cells, such as eosinophils and mast cells, as well as various cytokines, including TNF-α and IL-6, take part in the airway inflammatory response of asthma." (PMID 32929606, 2020). "A study indicated that the levels of cytokines (e.g., TNF-α) increased in cohorts with asthma and acute exacerbation (AE) of COPD." (PMID 32092112, 2020). "Using multiplex xMAP technology, we have further validated that the levels of the upstream cytokines of S1P signaling such as IL-13, IFN-γ, TNF-α, IL-4, IL-5, and IL-1β were increased in the serum of asthma patients." (PMID 32637407, 2020). "CAM attenuates airway inflammation via TNFα and IL-17A suppression in a mouse model of steroid-resistant asthma." (PMID 31820024, 2020). "Inhaled TNF-α increases bronchial responsiveness to methacholine in normal individuals and patients with asthma." (PMID 32117245, 2020). "Tumor necrosis factor-α (TNF-α), another cytokine implicated in both asthma and cardiovascular disease, at first appears to be a promising target for further research in targeting shared dysregulation in these two pathologies." (PMID 32194407, 2020). "A high number of positive correlations between the assessed cytokines and CHI3L1, IL-12p40, IL-1β, IL-6, IL-8, TNF in moDCs was observed in asthma and COPD." (PMID 32842623, 2020).
asthma (continued). "The levels of inflammatory factors including C-reactive protein (CRP), tumor necrosis factor-alpha (TNF-α), and interleukin-6 (IL-6) in peripheral serum of children with asthma were significantly higher than those in the controls." (PMID 32158441, 2020). "Casticin is reported to alleviate airway inflammation by suppressing pro-inflammatory cytokine production such as TNF-α in the lungs and bronchoalveolar lavage fluid in an inflammatory murine model of asthma." (PMID 32188443, 2020). "In our study, we evaluated the therapeutic effects of LOL on OVA-challenged asthma mice and TNF-α-stimulated NCI-H292 cells." (PMID 32605045, 2020). "TNFα 5'CGI is a potential epigenetic biomarker for uncovering a phthalate mechanism in childhood asthma research." (PMID 32435260, 2020). "A study on cytokines in bronchoalveolar lavage fluid reported that patients with active asthma had increased TNF-α and IL-6 levels than healthy controls and stabilized patients with asthma." (PMID 32999682, 2020). "The upstream regulator cytokines of S1P signaling such as IL-13, IFN-γ, TNF-α, IL-4, IL-5, and IL-1β were significantly (P < 0.01) increased in the serum of asthma patients compared the healthy controls." (PMID 32637407, 2020). "To understand how miR-146a expression is regulated in the airway epithelial cells, we stimulated primary cultured HBECs from healthy donors with cytokines associated with asthma pathogenesis, including IFN-γ, TNF-α, IL-17A, IL-22 and IL-4." (PMID 31798831, 2019). "The antiasthma simplified herbal medicine intervention (ASHMI) alleviates asthma symptoms by modulating Group 1 cytokine (inhibition of TNF-α and IL-6) and Group 2 cytokine (inhibition of IL-17, IL-13, IL-5, and IL-4, and enhancement of IFN-γ) expression." (PMID 31284537, 2019). "Inflammatory cells contribute to the pathogenesis of asthma by secreting pro-inflammatory cytokines including TNF-α, IL-6, and IL-1." (PMID 31143692, 2019). "Several pulmonary diseases including asthma, acute lung injury, COPD and acute respiratory distress syndrome (ARDS), are associated with abnormal TNF-α, IL-1β and IL-6 expression." (PMID 31395940, 2019). "A birth cohort study has shown the association of prenatal cytokine production (cord-blood concentrations of IL-4, IFN-γ, and tumor necrosis factor) with the development of atopy and asthma at 6 years of age." (PMID 31507589, 2019). "The present study examined the expression of proinflammatory cytokines known to be associated with inflammatory airway diseases such as asthma and COPD (IL-6, IL-8, and TNF-α mRNA) after apocynin treatment." (PMID 31612365, 2019). "Airway diseases such as asthma are triggered by inflammation and mediated by proinflammatory cytokines such as tumor necrosis factor alpha (TNFα)." (PMID 31512410, 2019). "TNF-α is also an important cytokine in patients with asthma and contributes to the inflammatory response in the asthmatic airway." (PMID 31692453, 2019). "Asthma exacerbations are often triggered by air pollution including ozone and in a murine model of asthma, ozone exposure resulted in enhanced AHR and greater neutrophilic inflammation associated with increased BAL levels of TNF-α, IL-13, and HA." (PMID 31354743, 2019). "The level of IL-1β (P < 0.05) and MDA in the serum and lung tissue (P < 0.01), (P < 0.05), and also the level of TNF-α (P < 0.05) in the lung tissue decreased in the Myrtenol group compared to the asthma group." (PMID 32641957, 2019). "Inflammation triggers asthma pathophysiology via pro-inflammatory cytokines such as tumor necrosis factor α (TNFα) and interleukin 13 (IL-13)." (PMID 32010691, 2019). "A role of mTOR in the onset of asthma has been proposed, and both the mTOR pathway and NF-kB are activated following TNFα/ IL-4 mediated stimulation in the bronchial epithelial cell line BEAS-2B." (PMID 29320511, 2018).